TUSC3 (tumor suppressor candidate 3)
Description:
Acts as accessory component of the N-oligosaccharyl transferase (OST) complex which catalyzes the transfer of a high mannose oligosaccharide from a lipid-linked oligosaccharide donor to an asparagine residue within an Asn-X-Ser/Thr consensus motif in nascent polypeptide chains. Involved in N-glycosylation of STT3B-dependent substrates. Specifically required for the glycosylation of a subset of acceptor sites that are near cysteine residues; in this function seems to act redundantly with MAGT1. In its oxidized form proposed to form transient mixed disulfides with a glycoprotein substrate to facilitate access of STT3B to the unmodified acceptor site. Also has oxidoreductase-independent functions in the STT3B-containing OST complex possibly involving substrate recognition. Could indirectly play a role in Mg(2+) transport.
Synonyms: N33; MGC13453; OST3A; MRT7; MagT2; SLC58A2; D8S1992; M33; MRT22
Tractability: Antibody: its Gene Ontology location is reachable by antibodies, with high confidence; UniProt predicts a signal peptide or a membrane-spanning region. PROTAC: ubiquitination databases record sites on it; its protein half-life has been measured.
Gene: Protein-coding gene on chromosome 8 (15,417,215 to 15,766,649, forward strand). Ensembl gene ENSG00000104723.
Subcellular location: Endoplasmic reticulum membrane
Pathways (Reactome):
Disease: Maturation of DENV proteins; Maturation of spike protein
Immune System: PD-L1(CD274) glycosylation and translocation to plasma membrane
Metabolism of proteins: Asparagine N-linked glycosylation
Transport of small molecules: Miscellaneous transport and binding events
Gene Ontology:
Molecular function: magnesium ion transmembrane transporter activity
Biological process: cognition; magnesium ion transport; protein N-linked glycosylation; magnesium ion transmembrane transport; transmembrane transport
Cellular component: oligosaccharyltransferase complex; endoplasmic reticulum membrane; mitochondrion; plasma membrane
Genetic constraint (gnomAD): Loss-of-function variants: 42 observed, 41.47 expected, observed/expected ratio (o/e) 1.01, 90% interval 0.79 to 1.31. The synonymous counts are far from expectation, so gnomAD's model fits this gene poorly and the ratio says little. Missense variants: 504 observed, 439.09 expected, observed/expected ratio (o/e) 1.15, 90% interval 1.07 to 1.24. Synonymous variants: 209 observed, 155.34 expected, observed/expected ratio (o/e) 1.35, 90% interval 1.2 to 1.51.
Gene-disease validity (ClinGen):
ClinGen rates the evidence that TUSC3 causes each of these diseases.
intellectual disability (autosomal recessive): Definitive.
Homologues: Orthologues: chimpanzee TUSC3 (100% identical), macaque TUSC3 (100% identical), pig TUSC3 (99% identical), dog TUSC3 (98% identical), mouse Tusc3 (98% identical), rat Tusc3 (98% identical), guinea pig TUSC3 (98% identical), tropical clawed frog tusc3 (84% identical), zebrafish tusc3 (79% identical), rabbit TUSC3 (78% identical), Drosophila melanogaster Ostgamma (53% identical), Caenorhabditis elegans ZK686.3 (43% identical). Paralogues in human: MAGT1 (64% identical).
Diseases named in the same sentence as TUSC3 in open-access papers:
TUSC3 is named in the same sentence as 68 diseases in open-access papers, as found by Europe PMC text mining. Sharing a sentence is not in itself a finding about the gene and the disease. The quoted sentences say what the papers report.
glioblastoma (13 papers, 2012 to 2025). The most malignant astrocytic tumor (WHO grade IV). "A study demonstrated that cancer stem cell like phenotype can be induced by targeting TUSC3 in glioblastoma through miR-132." (PMID 38992585, 2024). "As a tumor suppressor gene, it was reported that TUSC3 is related to the progression of glioblastoma by inhibiting the activity of the Akt signaling pathway." (PMID 36274132, 2022). "It has been reported that miR-132 promoted temozolomide resistance and glioblastoma initiating cells (GICs) phenotype formation by TUSC3 targeting in glioblastoma (GBM)." (PMID 34419060, 2021). "Among the individual signature genes, both HOXD10 and TUSC3 remained correlated with age in both data sets when limiting the analysis to IDH1 wild-type glioblastoma cases." (PMID 23046790, 2012). "One of the genes contributing to this trend, TUSC3, is known to be silenced by promoter methylation in glioblastoma, particularly in patients aged over 40 years." (PMID 23046790, 2012). "It has recently found that miR-132 could induce temozolomide resistance and promotes the formation of GIC phenotypes by targeting TUSC3 in glioblastoma initiating cells." (PMID 31906769, 2020). "Moreover, TUSC3 was reported to related to the development of different cancers, such as glioblastoma, colorectal cancer, pancreatic cancer, and so on." (PMID 27980454, 2016). "Tumor suppressor candidate 3 (TUSC3) inhibited tumorigenesis in ovarian cancer, prostate cancer, glioblastoma and pancreatic cancer but enhanced cancer progression in head and neck cancer and CRC." (PMID 34712608, 2021). "At the level of individual GNS signature genes, five were significantly associated with survival (P < 0.05) in both of the two largest glioblastoma data sets we investigated (TCGA and Gravendeel): HOXD10, PDE1C, PLS3, PTEN and TUSC3." (PMID 23046790, 2012). "Specifically, DDIT3, HOXD10, PDE1C and PLS3 were upregulated in GNS cells and expressed at higher levels in glioblastomas with poor prognosis, while PTEN and TUSC3 were downregulated in GNS cells and expressed at lower levels in gliomas with poor prognosis." (PMID 23046790, 2012).
colorectal cancer (11 papers, 2016 to 2025). A primary or metastatic malignant neoplasm that affects the colon or rectum. "TUSC3 epigenetic loss has been found in colorectal cancer, the same tumor type in which we initiated our screening, and it is associated with adverse prognosis." (PMID 30018746, 2018). "miR-873-5p inhibits the development of colorectal cancer by regulating TUSC3/AKT signaling." (PMID 40442738, 2025). "For example, TUSC3 activates WNT/β-catenin and MAPK signaling to improve the proliferation and migration of colorectal cancer (CRC) cell lines." (PMID 36274132, 2022). "It was reported that TUSC3 enhances EMT progress in colorectal cancer and non-small cell lung cells." (PMID 36274132, 2022). "Furthermore, silencing of tumor suppressor candidate 3 (TUSC3) mRNA expression by promoter methylation induces signaling of epidermal growth factor receptor (EGDR), which leads to colorectal cancer cells protection from apoptosis." (PMID 32370233, 2020). "For example, early study showed TUSC3 is not hypermethylated in colorectal carcinoma, however hypermethylation is the major mechanism for TUSC3 down-regulation in ovarian cancer and even carries a prognostic value." (PMID 26871953, 2016).
breast cancer (9 papers, 2008 to 2024). A primary or metastatic malignant neoplasm involving the breast. "The SOX2/miR-181a-5p, miR-30e-5p/TUSC3 axis is also identified as being closely linked with the proliferation and migration of breast cancer cells." (PMID 31462898, 2019). "TUSC3 is a putative tumor suppressor gene, and hypermethylation or loss of this gene has been found in cancers such as ovarian and breast cancer." (PMID 28288641, 2017). "Overexpression of these two microRNAs leads to reduced protein levels of Tumor Suppressor Candidate 3 (TUSC3) in breast cancer cells; mutations of the potential binding sites in the 3’-UTR of TUSC3 abrogate the inhibitory effects of the microRNAs." (PMID 28288641, 2017). "TUSC3 is a tumor suppressor whose loss or decreased expression is associated with the proliferation of several cancer types and is markedly under-expressed in breast cancer cells." (PMID 30557297, 2018). "Importantly, inversed expression of SOX2 and TUSC3 is associated with poor prognosis of a subpopulation of breast cancer patients." (PMID 28288641, 2017). "Conversely, Overexpression of miR-30e-decreased expression of Tumor Suppressor Candidate 3 (TUSC3) leads to increased proliferation and migration of breast cancer cells." (PMID 36275705, 2022). "We examined 12 pairs of normal and breast cancer biopsies, and found that 9 breast cancer biopsies have increased expression of SOX2 proteins concomitant with low levels of TUSC3." (PMID 28288641, 2017). "In human breast cancer samples the levels of TUSC3 protein are inversely correlated with those of SOX2 protein." (PMID 28288641, 2017). "Collectively, these results demonstrated that high levels of TUSC3 protein reduce the invasive potential of breast cancer cells." (PMID 28288641, 2017). "Consistently, overexpression of TUSC3 suppresses the proliferation and migration of breast cancer cells." (PMID 28288641, 2017). "We further found that upregulation of TUSC3 expression leads to reduced proliferation and migration of breast cancer cells." (PMID 28288641, 2017). "SOX2 was reported to promote breast cancer through targeting miR-181a-5p and miR-30e-5p/TUSC3 axis." (PMID 38864530, 2024). "We next asked whether increased levels of TUSC3 are also able to reduce the migration of breast cancer cells." (PMID 28288641, 2017). "To test whether TUSC3 acts as a negative regulator of proliferation and migration of breast cancer cells, we performed TUSC3 gain-of-function study." (PMID 28288641, 2017). "In addition, overexpression of TUSC3 decreases the proliferation and migration capabilities of breast cancer cells." (PMID 28288641, 2017). "Therefore we demonstrate here a clinically relevant axis which involves SOX2/miRNAs/TUSC3 in breast cancer development." (PMID 28288641, 2017). "Here, we show decreased but not complete loss of TUSC3 protein in breast cancers, suggesting that promoter methylation is unlikely a significant contributor to disease progression." (PMID 28288641, 2017). "Along these lines our study indicates that high levels of TUSC3 expression may induce a cellular response of breast cancer cells, resulting in reduced cell proliferation and migration." (PMID 28288641, 2017). "In addition, TUSC3 overexpression significantly inhibits the colony formation efficiency (274 ± 6 Vs 119 ± 4 colonies/well) in 6-well plates (p < 0.01) and reduces the size of individual colonies (p < 0.05), suggesting that TUSC3 acts as a negative regulator of proliferation of breast cancer cells." (PMID 28288641, 2017). "Consistently, overexpression of TUSC3 reduces the proliferation and migration of SOX2-high breast cancer cells." (PMID 28288641, 2017). "In this study we examined the molecular mechanisms used by SOX2 in the proliferation and migration of breast cancer cell lines and identified that SOX2 regulates two miRNAs (miR-181a-5p and miR30e-5p) which in turn influence the expression of a common downstream target TUSC3." (PMID 28288641, 2017).
ovarian carcinoma (9 papers, 2008 to 2022). A malignant neoplasm originating from the surface ovarian epithelium. "Previous work has shown decreased TUSC3 expression at mRNA level is associated with higher grade of ovarian cancer." (PMID 26871953, 2016). "Loss of TUSC3 can destabilize the rough ER system and induce inflation of the cisternae system and alters ER stress response signaling in prostate cancer and ovarian cancer." (PMID 26871953, 2016). "Loss of heterozygosity on chromosomal band 8p22 and decreased gene expression of TUSC3 has been associated with an increase of metastatic potential in prostate, colorectal, and ovarian cancer." (PMID 18822129, 2008). "Loss of TUSC3 enhances proliferation and migration of ovarian cancer cells in vitro." (PMID 28272772, 2017). "In ovarian cancer cells loss of TUSC3 induces ER stress and morphological alterations in the ER." (PMID 28288641, 2017). "TUSC3 has been reported in a variety of cancers, such as prostate cancer, ovarian cancer, and pancreatic cancer, and its effects on cell proliferation, migration, and invasion have also been validated." (PMID 36274132, 2022). "TUSC3 is a putative tumour suppressor often lost in epithelial cancers e.g. ovarian cancer and head and neck squamous cell carcinomas." (PMID 28288641, 2017). "Promoter methylation leading to silencing of TUSC3 gene was considered as a poor prognostic factor in ovarian cancer." (PMID 28288641, 2017). "Pils 6 proved that TUSC3 hypermethylation correlates with the survival of patients, indicating that TUSC3 is an accepted marker of poor prognosis in ovarian cancer patients." (PMID 28272772, 2017). "Later on, it was discovered that TUSC3 mRNA down-regulation originates from hypermethylation of its promoter, and the methylation status has a prognostic value in ovarian cancer." (PMID 26871953, 2016). "In ovarian, TUSC3 was also found to be significantly down-regulated in higher-grade ovarian cancer specimens." (PMID 26871953, 2016). "Previously, TUSC3 down-regulation has been demonstrated due to homozygous and heterozygous deletion in prostate cancer, promoter hypermethylation in ovarian cancer." (PMID 26871953, 2016). "Taken together, the dramatic up-regulation of RAB25 and down-regulation of TUSC3 in RIα cells appears to faithfully mimic the activity profiles of proven markers of ovarian cancer clinical progression." (PMID 18822129, 2008). "In particular, TUSC3 showed significantly lower expression in grade 3 primary ovarian carcinoma tumors compared with tumors of lower grade or compared with normal controls." (PMID 18822129, 2008). "Significantly lower expression of TUSC3 was correlated with an increase in clinical grade severity in a study of 58 primary ovarian carcinoma tissues." (PMID 18822129, 2008). "On the contrary, it was also reported that TUSC3 prevents the EMT process in ovarian cancer." (PMID 36274132, 2022). "In addition, loss of TUSC3 modifies the molecular response to ER stress and causes characteristics of the epithelial-to-mesenchymal transition (EMT) in ovarian cancer cells." (PMID 36274132, 2022). "Further study showed its low expression results from TUSC3 promoter hypermethylation and the methylation status of the TUSC3 promoter has a significant and independent influence on progression free and overall survival for ovarian cancer patients." (PMID 26871953, 2016). "In Krainer’s paper on ovarian cancer, decreased TUSC3 was regarded as involved in insufficient N-glycosylation of target proteins, which may influence the normal function of these molecules." (PMID 26871953, 2016). "Studies on ovarian cancer cell lines and tumor specimens showed that the TUSC3 expression was significantly downregulated in ovarian cancer due to hypermethylation of the TUSC3 promoter region, and deletion of TUSC3 could promote proliferation and metastasis of ovarian cancer cells." (PMID 34733314, 2021).
pancreatic cancer (9 papers, 2016 to 2022). "Participants with two copies of the Tumor Supressor Candidate 3, TUSC3, had a 20% increased odds of pancreatic cancer compared to individuals with germline hemizygous deletions in this gene (90% credible interval (CI) for odds ratio: 1.01 - 1.39)." (PMID 32894098, 2020). "The main effector pathway of TUSC3 previously shown in prostate, ovarian and pancreatic cancer cells comprised the control of the ER stress response via modulation of MGAT enzymes and BCL family proteins, involved in cell survival and regulation of apoptosis." (PMID 29156678, 2017). "TUSC3-silenced pancreatic cancer cell line exhibited enhanced potential of proliferation, migration and invasion." (PMID 26871953, 2016). "The current study shows that TUSC3 expression is decreased in pancreatic cancer primary specimens and its down-regulation is prognostic of poor long-term outcome." (PMID 26871953, 2016). "As early as in 2005, homozygous and heterozygous deletion of TUSC3 gene was discovered in pancreatic cancer cell lines and specimens with genomic array-based studies." (PMID 26871953, 2016). "To characterize the in vitro function of TUSC3, we firstly examined the TUSC3 expression of different pancreatic cancer cell lines." (PMID 26871953, 2016). "The results are consistent and confirmed that TUSC3 is dramatically depressed in pancreatic cancer, both in primary specimens and in tumor cell lines, both at mRNA level and protein level." (PMID 26871953, 2016). "In conclusion, the current study shows that decreased immunological TUSC3 staining is a factor prognostic of poor survival in pancreatic cancer patients and decreased TUSC3 promotes pancreatic cancer cell proliferation, invasion and metastasis." (PMID 26871953, 2016). "Real-time PCR revealed TUSC3 was decreased at mRNA level in all the tested 11 pancreatic tumor cell lines." (PMID 26871953, 2016). "More interestingly, TUSC3 had reverse correlation with NF-κB activity at least in some pancreatic tumor cell lines and is in consistence with the different degrees of malignancy." (PMID 26871953, 2016). "To explore whether TUSC3 expression is correlated with NF-κB activity, we examined the TUSC3 expression both at RNA level and protein level in three pairs of pancreatic cancer cell lines with different NF-κB activity." (PMID 26871953, 2016). "Distinct from other studies which examined mRNA expression, our study detected TUSC3 expression at protein level in primary specimens and correlated it with pancreatic cancer TNM staging and long-term outcome and confirmed that its immunohistochemical staining has a prognostic role for this disease." (PMID 26871953, 2016). "This study demonstrated that decreased TUSC3 expression is associated with higher TNM staging in pancreatic cancer and is an independent prognostic factor predictive of poor long-term outcome for resected pancreatic cancer patients." (PMID 26871953, 2016). "TUSC3 expression was observed to various degrees in pancreatic carcinoma cells in cytoplasm." (PMID 26871953, 2016). "Then, Matrigel based assay was used to analyze the effects of TUSC3 knockdown on migration and extracellular matrix (ECM) invasion of pancreatic cancer cells." (PMID 26871953, 2016). "TUSC3 (tumor suppressor candidate 3) was identified as a potential tumor suppressor gene and previous study showed TUSC3 is decreased in pancreatic cancer at mRNA level, but its putative tumor suppressor function remains to be verified." (PMID 26871953, 2016). "Thirdly, the current study does not explore how TUSC3 plays the tumor suppressor role in pancreatic cancer progression or the downstream signaling pathway." (PMID 26871953, 2016). "Using the methods outlined in this study, we found that germline deletions of TUSC3 and near MYC were more prevalent among participants without pancreatic cancer." (PMID 32894098, 2020).
colon cancer (7 papers, 2020 to 2024). "The regulation of TUSC3 gene expression through epigenetics was considered as a critical factor in the progression of colon cancers at cellular level." (PMID 38992585, 2024). "MiR-873-5p has been proved as a tumor suppressor in papillary thyroid cancer by targeting CXCL16 and in colon cancer via the inhibition of TUSC3." (PMID 35241028, 2022). "Recently, Taniue and colleagues reported that TUSC3 expression induced by HBO1 via histone acetylation is critical for colon cancer cell proliferation." (PMID 33754016, 2021). "For instance, it inhibits colon cancer by inhibiting TUSC3/AKT signal transduction and inhibits rectal cancer progression via targeting ZEB1 to regulate epithelial-mesenchymal transition." (PMID 33102581, 2020). "Recent research suggests that CCAT1 promotes colon cancer cell growth by increasing expression of the oncoprotein c-MYC and the oncogenic mRNA tumor suppressor candidate 3 (TUSC3), the target of miR-181b-5p in CRC cells, thus increasing glucose metabolism to fuel colon cancer cell growth." (PMID 37568815, 2023).